AR (androgen receptor)
Diseases named in the same sentence as AR in open-access papers (continued):
Sharing a sentence is not in itself a finding about the gene and the disease.
lung carcinoma (continued). "Subsequently, we performed qRT-PCR analysis to assess the expression of these genes in two lung cancer cell lines after AR manipulation." (PMID 37564195, 2023). "Collectively, the results from our study suggest that AR can suppress lung cancer cell invasion and increase DDP response by modulating the circ-SLCO1B7/miR-139-5p/TPD52 signaling pathway." (PMID 37564195, 2023). "In this study, we aimed to investigate the downstream signaling molecules responsible for the suppressive role of AR in lung cancer cell progression." (PMID 37564195, 2023). "CPTAC database also revealed that lung cancer samples selected to express AR protein at a relatively low level." (PMID 37564195, 2023). "HNF1A, ALX1, AR, and GR play certain roles in lung cancer development and progression, and/or they have been associated with the overall survival." (PMID 36832225, 2023). "Subsequently, we conducted a ChIP assay to confirm the binding of AR to the putative AREs in lung cancer cells." (PMID 37564195, 2023). "To investigate the functional role of AR in lung cancer, we first efficiently overexpressed AR (oeAR) into H1299 and A549 cells." (PMID 37564195, 2023). "The in vivo data also validated the functional contribution of AR/circ-SLCO1B7/miR-139-5p/TPD52 axis to lung cancer progression." (PMID 37564195, 2023). "After the phosphorylation site of AR protein 877 was inactivated, the ability of luteolin to inhibit the proliferation of lung cancer cells was weakened." (PMID 37716981, 2023). "The significance of AR expression in CAFs in NSCLC should be examined in conjunction with androgen concentration in lung cancer tissues." (PMID 37509283, 2023). "FOXA1 is also involved in pancreatic cancer, lung cancer, liver cancer and other solid tumors by regulating AR and ER signaling pathways." (PMID 34991620, 2022). "More recently, a direct link between AR expression and epithelial to mesenchymal transition in lung cancer patients has been reported, and a correlation between AR overexpression and breast, ovarian, cervical, and rectal cancer was discovered." (PMID 36230882, 2022). "AR is expressed in several types of lung cancer, including small cell, adenocarcinoma, and squamous cell carcinoma, and dihydrotestosterone (DHT) induces a proliferative response in lung cancer cells through cross‐talk of AR and EGFR." (PMID 33350105, 2022). "Similar functional effects of miR-99b-5p on AR/mTOR inhibition, mTOR localization, and apoptosis induction were also shown in colon, breast, and lung cancer cell models." (PMID 36077039, 2022). "Various studies have investigated the role of AR, suggesting its importance in the initiation and advancement of lung cancer." (PMID 35631448, 2022). "Maasberg and colleagues showed that treatment with testosterone, an AR agonist, resulted in growth stimulation up to 3-fold in five different lung cancer cell lines examined with positive AR expression." (PMID 35631448, 2022). "In a lung cancer tissue array, it was found that distinct types of lung cancer are androgen receptor-positive, indicating that in addition to prostate tissues, androgen signaling also targets the lung to enhance the expression of TMPRSS2." (PMID 34001144, 2021). "We selected drug-resistant variants of the previously tested MCF7 breast and H69 lung cancer cell lines: MCF7 Pgp and H69 Lx4, which overexpress Pgp, and H69 AR, which overexpresses MRP1." (PMID 35582609, 2020). "It was clarified that the core components namely ismine, 5-hydroxy-7-methoxy-2-methylchromone, pluviine, and acetyllycoramine have multi-target mechanisms in mitigating lung cancer through the inhibition of AR, EGFR and ESR-1 proteins with involvement of 39 putative pathways." (PMID 39888361, 2025). "A459, the only lung cancer cell that we tested, has been shown to express AR." (PMID 40940976, 2025).
lung carcinoma (continued). "Furthermore, the androgen receptor (AR), which is primarily expressed in pneumocytes and lung epithelium in male patients, plays an essential role in the etiology of lung cancer." (PMID 39725665, 2024). "Previous studies have provided evidence that AR can inhibit the progression of lung cancer cells." (PMID 37564195, 2023). "Furthermore, a correlation was observed between the stage of lung cancer and the level of AR, with higher tumor stages showing lower AR expression levels." (PMID 37564195, 2023). "Western blot showed that luteolin could inhibit AR protein expression in lung cancer cell line A549." (PMID 37716981, 2023). "However, our data also indicated that the reversal of AR regulated TPD52 expression by miR-139-5p was only partial, suggesting that sponging miR-139-5p is just one of the signaling pathways involved in the AR-circ-SLCO1B7-mediated lung cancer progression." (PMID 37564195, 2023). "Hence, we compared TMPRSS2 and AR basal protein expressions in two lung cancer cell lines (A549 and Calu-3) versus two PCa cells lines (VCaP and LNCaP) by Western blot." (PMID 36834705, 2023). "The results demonstrated that hsa_circ_0008705 (circ-CABYR) and hsa_circ_0025583 (circ-SLCO1B7) consistently displayed changes in expression in response to AR manipulation, suggesting a potential regulatory role of AR in modulating the expression of these circRNAs in lung cancer cells." (PMID 37564195, 2023). "Some studies have found that AR may play an important role in lung cancer biology, however, the role of AR signals in the progression of sex-unrelated cancers presents a complex situation and evidence remains contradictory." (PMID 37716981, 2023). "However, most recent studies provide new evidence for AR–miRNA crosstalk, even in diseases such as lung cancer, liver cancer, and renal cancer, among others." (PMID 35163477, 2022). "These population-level findings support a role of the androgen receptor in lung cancer." (PMID 35804979, 2022). "These real-world data support the hypothesis implicating androgen receptor signaling as a potential therapeutic target in lung cancer." (PMID 35804979, 2022). "Despite the high similarity in the sex hormone pathway signaling cascade and the downstream consequences of both androgen and estrogen receptor perturbation by their ligands, the role of androgen receptor expression and signaling in lung cancer pathogenesis remains to be carefully studied." (PMID 35804979, 2022). "Additionally, androgen receptor expression has been characterized in archival samples of human lung cancer tissue, and its expression appeared to counteract the negative impact of high Ki67 expression in these patients." (PMID 35804979, 2022). "When AR antagonists such as flutamide and cyproterone acetate were used to treat, they antagonized the growth stimulatory effects of testosterone, suggesting that testosterone possesses an ability to stimulate the growth of lung cancer cells." (PMID 35631448, 2022). "Androgen receptor (AR) expression is frequently observed in human lung cancer tissues." (PMID 35657341, 2022). "Various lines of evidence implicate androgen receptor signaling to lung cancer biology." (PMID 35804979, 2022). "Next, we further investigated whether the miR-99b-5p can target/inhibit the AR/mTOR axis and promote cell apoptosis and/or enhance the docetaxel-induced cytotoxicity in colon, breast, and lung cancers." (PMID 36077039, 2022). "Liang Feng and Meng Xiansheng used the MTT method to determine the inhibitory rate of the extract of AR on the proliferation of human lung cancer A549 cells, and the results showed that the extract of AR had a significant inhibitory effect on the A549 cells with IC50 of 133.5 g/mL." (PMID 34887934, 2021). "The androgen receptor is also expressed by ovarian and lung cancer tumors and cell lines." (PMID 33585078, 2021).
lung carcinoma (continued). "In addition, studies have shown that the total flavonoids of AR can inhibit the proliferation and apoptosis of lung cancer A549 cells." (PMID 34887934, 2021). "Positive expression of AR might be correlated with the progression and the lymph node metastasis of lung cancer." (PMID 31905767, 2019). "The top network in this subset displayed a centrality of the androgen receptor (AR), not generally implicated in lung cancer to date." (PMID 26683690, 2015). "As expected, our quantification analyses were consistent with the IVIS signal observed earlier, demonstrating a higher number of metastatic foci in the shAR group compared to the control group, which could be attenuated in counterparts bearing lung cancer with depletion of both AR and circ-SLCO1B7." (PMID 37564195, 2023). "However, the relationship between AR and the biology of circRNA regarding to lung cancer cell invasion and cisplatin response remains unclear." (PMID 37564195, 2023). "In the present study, we found that lung cancer A549 cells could express androgen receptor (AR)." (PMID 37716981, 2023). "Evidence of AR expression in type II pneumocytes, bronchial epithelial cells, and lung cancer cells suggests that androgens themselves may play a direct role in the development of lung cancer." (PMID 30121970, 2018). "Therefore, it is possible that ADT may exert an immunomodulatory effect on AR-expressing lung cancer cells." (PMID 30121970, 2018). "In A549 cells, an NSCLC cell line with relatively high AR expression, AR and EGFR (a crucial oncogene in lung cancer) collaboratively promote proliferation by activating p38 MAPK signaling." (PMID 41228208, 2025). "Multiple under-expressed proteins were also predictable to a great extent, the top-performing ones being CASP8, MET, BCL2, and SETD2 in BRCA; AR and TFRC in gastric cancer; and VHL in lung cancer with AUCs ranging 0.814–0.866." (PMID 38491101, 2024). "In our study, we confirmed that TPD52 indeed acts as an oncogene and is regulated by the AR/circ-SLCO1B7/miR-139-5p signaling pathway, promoting lung cancer progression." (PMID 37564195, 2023). "Specifically, we found that AR-regulated circ-SLCO1B7, a circular RNA molecule, plays a significant role in lung cancer cell invasion and response to cisplatin." (PMID 37564195, 2023). "This androgen receptor (AR)–dependency of TRPM8′s role in proliferation has also been observed in cells from other cancers, such as colon, osteosarcoma, and lung cancer." (PMID 35743115, 2022). "The other genes AR, ATF2, CUL1, EP300, GATA4, LEF1, SKP2 in these subnetworks have also been identified as important in lung cancer." (PMID 24369052, 2013). "A total of 83 potential targets of ROB in lung cancer were collected and further screened by using Cytoscape software, and 7 targets of PTGS2, CYP19A1, PTGS1, AR, CYP17A1, PTGES and SRD5A1 were obtained as hub genes and 7 hub targets had good binding energy with ROB." (PMID 39450260, 2024). "Moreover, ANRIL expression is likely to be repressed by different factors, including Androgen Receptor (AR) and Phospholipase D (PLD) in prostate and lung cancer, respectively." (PMID 37627188, 2023). "Therefore, we decided to focus on TPD52 for further investigation regarding its potential links to AR, circ-SLCO1B7 and miR-139-5p in lung cancer progression." (PMID 37564195, 2023). "In these reports, several mechanisms have been proposed, including the induction of cyclin D1 expression in alveolar cells by AR, crosstalk between AR and EGFR, direct effects on lung cancer growth, polarization of macrophage M2, and increased susceptibility to cytotoxic T cells." (PMID 37509283, 2023). "AR‐positive staining was found in human PCa PC346C cells, and at a lower level in PCDF‐1 cells, while AR staining was absent in human lung cancer SW1573 cells." (PMID 29808619, 2018). "The data suggest that there is a correlation between the AR and EGFR functions in lung cancer." (PMID 15870715, 2005).
lung carcinoma (continued). "This study identifies ERα, ERβ and AR expression patterns in patients with lung cancer and PD-L1 negative and positive profiles and analyzing whether the association between these hormonal receptors and PD-L1 expression exists." (PMID 40612952, 2025). "The hub targets of ROB action in lung cancer were further analyzed by combining 14 targets from Degree≥6, 10 targets each from MCC and MNC algorithms, and finally 7 common targets such as PTGS2, CYP19A1, PTGS1, AR, CYP17A1, PTGES and SRD5A1 were obtained from the final screening." (PMID 39450260, 2024). "Surprisingly, in AR/TMPRSS2 double-positive H2126 and H1437 lung cancer cells, neither AR inhibition using enzalutamide nor AR stimulation using DHT resulted in a significant change in TMPRSS2 expression, implying that AR cannot regulate TMPRSS2 expression in human lung cancer cells." (PMID 33558541, 2021). "Moreover, this study suggests that the activation of the mammalian target of rapamycin (mTOR)/CD1 pathway by p38 mitogen-activated protein kinase (MAPK) might be the approach for AR and epidermal growth factor receptor (EGFR) cross-talk, leading to lung cancer development." (PMID 35631448, 2022). "Utilizing multiple models, including human lung cancer cells, human lung organoids and Ad-ACE2-transduced WT mice, we demonstrated that enzalutamide failed to inhibit SARS-CoV-2 infection, which was attributed to the lack of AR-driven modulation of TMPRSS2 expression in lung epithelial cells." (PMID 33558541, 2021).
hyperandrogenism (70 papers, 2010 to 2025). Excessive secretion of androgens from the adrenal glands or gonads. "Consequences of upregulated AR expression in human granulosa and theca cells are strongly linked to hyperandrogenism and polycystic ovary syndrome (PCOS), as women with PCOS frequently exhibit elevated AR levels and androgen activity." (PMID 40362320, 2025). "Many of the complications in PCOS are believed to be driven by hyperandrogenism, and previous studies show that a global loss of AR signaling fully protects female mice from the development of PCOS-like metabolic traits on excess androgen exposure." (PMID 38169733, 2023). "Most women diagnosed with PCOS present with hyperandrogenism; thus, disruption in AR expression is also implicated in abnormal folliculogenesis and anovulation." (PMID 35885010, 2022). "Furthermore, animal experiments have validated that melatonin can regulate key genes associated with hyperandrogenism, including AR and CYP19A1." (PMID 40838208, 2025). "Interestingly, studies in mice have shown that inactivating AR signalling in ovarian theca cells only partially prevented the development of hyperandrogenism-associated ovulatory dysfunction and PCOS-like features." (PMID 37171897, 2023). "AR appears to inhibit neutrophils and can cause neutropenia in AR-knockout male mice, but anti-androgens are also reported to reduce excessive levels of neutrophils in females with hyper hyperinsulinaemic hyperandrogenism." (PMID 37435460, 2022). "The most important etiopathogenesis factor in its incidence is hyperandrogenism; over 70 candidate genes are known to be associated with this syndrome, such as the androgen receptor (AR) gene which encodes a steroid receptor and is located on the Xq11-12 chromosome." (PMID 35571498, 2021). "Women with PCOS may be associated with hyperandrogenism, which may consequently induce aberrant expression of both AR and HOXA10 in the endometrium." (PMID 34053455, 2021). "Instead, we propose that hyperandrogenism is at the root of adipose tissue dysfunction, which is supported by the finding that normal serum adiponectin levels are maintained by a global loss of androgen receptor function in a hyperandrogenized PCOS mouse model." (PMID 33067453, 2020). "Transgenic mice with a neuron-specific deletion of AR, driven by CamKllα-Cre, enabled us to investigate the role of the brain in mediating prenatal androgen excess." (PMID 41206009, 2025). "Androgen receptor (AR) antagonists and 5-alpha-reductase inhibitors are being explored as more targeted therapies for hyperandrogenism in PCOS." (PMID 40357783, 2025). "When DBP is paired with testosterone (T) and E2, it maintains AR activation within the nucleus, resembling conditions of hyperandrogenism." (PMID 41009332, 2025). "Female PPA mice with a neuron-specific knockout of AR (NeurARKO) exhibit amelioration of androgen excess-induced reproductive and metabolic dysfunction, highlighting the brain as a key mediator of androgen excess." (PMID 41206009, 2025). "Androgen receptor sensitivity or androgen excess has been recognized as the dominant etiology for both AGA and acne." (PMID 39655323, 2024). "In the liver, BMAL1 inhibits GLUT4 expression, whereas period (PER1/2) interferes with AR and the production of hepatic IGFBP4 and SHBG, ultimately causing IR and androgen excess." (PMID 38152131, 2023). "Hyperandrogenism leads to increased expression of AR and implantation failure due to aberrant expression of genes related to implantation and mitochondrial function." (PMID 37569402, 2023). "Two alternative splice variants (ASVs), Ins-AR and Del-AR, have been identified exclusively in the GCs of patients with PCOS and are closely associated with hyperandrogenism and ovarian dysfunction." (PMID 38152131, 2023). "Hyperandrogenism and the resulting high expression of AR have been found to lead to defects in uterine cells due to aberrant expression of genes related to implantation and mitochondrial function." (PMID 37569402, 2023).